YTHDF2 (YTH N6-methyladenosine RNA binding protein F2)
Diseases named in the same sentence as YTHDF2 in open-access papers (continued):
Sharing a sentence is not in itself a finding about the gene and the disease.
melanoma (continued). "In melanoma, FTO knockdown increases m6A methylation of key oncogenes like PD‐1, CXCR4 and SOX10, promoting YTHDF2‐mediated mRNA degradation and making melanoma cells more susceptible to interferon‐γ and anti‐PD‐1 therapy." (PMID 39135292, 2024). "Similar mechanisms have been observed in melanoma and rectal cancer studies, where FTO downregulation led to increased m6A methylation levels in key genes, resulting in enhanced RNA degradation by YTHDF2." (PMID 38995602, 2024). "This reduction in YTHDF2 levels allows for the stabilization of BMP2 mRNA and subsequent activation of AKT phosphorylation, promoting melanoma cell proliferation and migration." (PMID 39377984, 2024). "YTHDF2 enhances the secretion of perforin, granzyme B and IFN‐γ, thereby regulating melanoma metastasis within the TIME." (PMID 39135292, 2024). "In melanoma, knockdown of FTO promotes YTHDF2-mediated PD-1, CXCR4, and SOX10 mRNA decay, sensitizing melanoma cells to interferon-gamma and anti-PD-1 therapy." (PMID 36859310, 2023). "Briefly, YTHDF2 promotes the secretion of perforin, granzyme B, and IFN-γ, and decreases melanoma metastasis." (PMID 35254013, 2022). "In GEO datasets, except YTHDC2, other m6A readers like YTHDF1, YTHDF2, YTHDF3 and YTHDC1 have a significant higher expression in melanoma tissues." (PMID 36324258, 2022). "In summary, we have demonstrated that FTO inhibition suppresses melanoma tumorigenicity and the expression of melanoma cell-intrinsic genes PD-1 (PDCD1), CXCR4, and SOX10, at least partially through YTHDF2-mediated mRNA decay." (PMID 31239444, 2019). "Knockdown of FTO increases m6A methylation in the critical protumorigenic melanoma cell-intrinsic genes including PD-1 (PDCD1), CXCR4, and SOX10, leading to increased RNA decay through the m6A reader YTHDF2." (PMID 31239444, 2019). "In melanoma, FTO impairs IFNγ-induced killing in melanoma cells in vitro via up-regulating PD-1, CXCR4, and SOX10 through suppressing YTHDF2-mediated-degradation and inhibits response to anti-PD-1 blockade immunotherapy." (PMID 31801551, 2019). "In addition to inhibiting YTHDF2 phosphorylation, we observed that UVB down-regulates YTHDF2 protein in multiple cell lines and primary keratinocytes including HaCaT, CHL-1 (melanoma cells), HeLa, and NHEK cells." (PMID 41224760, 2025). "Additionally, western blot analysis revealed that the expression of three vital proteins that regulate m6A modification, namely METTL3, YTHDF2, and YTHDC1, was reduced in melanoma cells after DHPS knockdown." (PMID 38952061, 2024). "However, contrary conclusions were reported in melanoma, osteosarcoma, and CRC, where YTHDF2 acted as a tumor suppressor." (PMID 35382893, 2022). "In melanoma, inhibition of FTO suppresses tumorigenicity and increases the m6A levels in PD-1, CXCR1, and SOX10, hence enhancing the decay of these m6A-targeted mRNAs by YTHDF2." (PMID 35254013, 2022). "Remarkably, inhibition of FTO in melanoma has been found to suppress tumorigenicity and to increase the m6A levels in PD-1, CXCR1, and SOX10, hence enhancing the decay of these m6A-targeted mRNAs by YTHDF2." (PMID 35254013, 2022). "Theoretically, targeted overexpression of Mettl-3 might also control melanoma progression by decreasing FTO via balancing mechanism, and also by directly inhibiting the expression of pro-tumorigenic genes via recruiting YTHDF2 reader proteins." (PMID 34571899, 2021). "Yang and colleagues found that knocking down only YTHDF2 significantly increased the mRNA stability of PD-1 (PDCD1), CXCR4, and SOX10; in conjunction, the proliferative and migratory capacities of the melanoma cells were increased (in vitro) as was tumor growth (in vivo)." (PMID 34105069, 2021).
melanoma (continued). "In addition, FTO level was found to be increased in human melanoma, knockdown of which increases m6A methylation in PD-1, CXCR4, and SOX10, leading to increased RNA decay through the m6A reader YTHDF2." (PMID 33611339, 2021). "Additionally, YTHDF2 and YTHDF3 facilitated melanoma progression through distinct mechanisms." (PMID 41301778, 2025). "Knockdown of FTO increases m6A methylation of PD-1 in melanoma cells, while deletion of ALKBH5 (the ‘eraser’ of m6A) enriches the 3’UTR region of PD-L1 mRNA with m6A modifications, thereby promoting the degradation of PD-1 and PD-L1 in a YTHDF2-dependent manner." (PMID 35309316, 2022). "Subsequent studies revealed that METTL3 could not regulate the expression of YTHDC1/YTHDF2 proteins in melanoma, which also predicts that the methylation modifications regulated by METTL3 are not required for all genes, but that METTL3‐mediated m6A‐methylation modification is dependent on DHPS." (PMID 38952061, 2024).
glioblastoma (49 papers, 2020 to 2025). The most malignant astrocytic tumor (WHO grade IV). "The expression of YTHDF2 is elevated in glioblastomas and is associated with an unfavorable patient survival." (PMID 38398118, 2024). "In glioblastoma (GBM) stem cells, METTL3 and YTHDF2 have been implicated in Yin Yang 1 (YY1)-mediated IFN-β signaling and antigen presentation through m6A methylation, reducing Treg cell infiltration and improving the efficacy of immune checkpoint therapy." (PMID 39987091, 2025). "In contrast, the EGFR/SRC/ERK signaling pathway can phosphorylate and stabilize the m6A reader protein YTHDF2, which is necessary to sustain the invasive, proliferative, and tumorigenic properties of glioblastomas." (PMID 40612868, 2025). "To confirm the role of YTHDF2 in PRMT6-induced malignant phenotypes in glioblastoma, we used YTHDF2-overexpressing lentivirus to infect PRMT6-knockdown stable cell lines, creating a double-stable cell model for rescue experiments." (PMID 38637831, 2024). "Wound healing assays showed that silencing YTHDF2 significantly inhibited, while overexpressing YTHDF2 enhanced, glioblastoma cell migration." (PMID 38637831, 2024). "This suggests that PRMT6 promotes glioblastoma’s malignant traits via YTHDF2-mediated activation of the Wnt-β-catenin pathway." (PMID 38637831, 2024). "Treatment with 20μM EPZ020411 for 24 h resulted in decreased mRNA expression of YTHDF2 in glioblastoma cell lines." (PMID 38637831, 2024). "In 2019, a new study validated earlier discoveries by demonstrating elevated METTL3 and YTHDF2 levels in samples from glioblastoma patients as compared with normal brain tissues." (PMID 38398118, 2024). "The study also confirmed that the survival outcomes of glioblastoma patients correlate with the expression levels of YTHDF2." (PMID 38398118, 2024). "Knockdown of YTHDF2 in glioblastoma and GSC cells impeded both cell proliferation and DNA replication, suggesting that YTHDF2 protein is essential for glioblastoma cell proliferation." (PMID 38398118, 2024). "In glioblastoma stem cells, YTHDF2 plays a role in maintaining its oncogenic phenotype by stabilizing MYC and Vascular Endothelial Growth Factor (VEGF)." (PMID 39342406, 2024). "In summary, YTHDF2 is highly expressed in glioblastoma, correlates with poor prognosis, and promotes malignant progression of the disease." (PMID 38637831, 2024). "To clarify YTHDF2’s role in glioblastoma progression, we revisited its expression and prognostic data in public databases like TCGA and CGGA." (PMID 38637831, 2024). "At both mRNA and protein levels, YTHDF2 expression was higher in glioblastoma cell lines compared to normal human brain glial cells (HEB)." (PMID 38637831, 2024). "Knockdown of CDK9 or selective CDK9 inhibitors reduced YTHDF2 expression levels in glioblastoma stem cells, consistent with our findings." (PMID 38637831, 2024). "In another study, YTHDF2 was found to increase UBX domain protein 1 (UBXN1) mRNA degradation in glioblastoma cells." (PMID 38398118, 2024). "Investigations were conducted to unravel the process behind the elevated expression of YTHDF2 in glioblastoma." (PMID 38398118, 2024). "YTHDF2 has been shown to contribute to glioblastoma cell proliferation and tumorigenesis, and overexpression was mediated in glioblastoma via the EGFR/SRC/ERK pathway." (PMID 37444417, 2023). "YTHDF2 in glioblastoma mediated the degradation of UBX domain protein 1, in turn inducing NF-KB activation." (PMID 37444417, 2023). "They discovered that epidermal growth factor receptor (EGFR) activation plays a role in m6A modification in glioblastoma and YTHDF2 overexpression occurred through the EGFR/SRC/ERK pathway." (PMID 35625706, 2022). "Meanwhile, Huang’s group explored the mechanism responsible for the overexpression of YTHDF2 in glioblastoma." (PMID 35625706, 2022). "Different from our findings and other studies, a recent study reported that YTHDF2 maintains the viability of glioblastoma stem cells by stabilizing MYC mRNA." (PMID 34544449, 2021).
glioblastoma (continued). "YTHDF2 has been found to regulate glucose metabolism via the stabilization of the proto-oncogene MYC in glioblastoma stem cells." (PMID 34093133, 2021). "In glioblastoma, in contrast to its proposed role, YTHDF2 was shown to stabilize MYC and VEGFA to maintain the oncogenic phenotype of glioblastoma stem cells." (PMID 33795663, 2021). "YTHDF2 expression upregulated in anaplastic oligoastrocytoma, with a fold change of 2.433, and downregulated in glioblastoma, with a fold change of –2.762." (PMID 32986017, 2020). "Moreover, in glioblastoma, YTHDF2 undergoes phosphorylation at serine 39 and threonine 381 through EGFR/SRC/ERK signaling pathway." (PMID 39342406, 2024). "YTHDF2 is particularly significant in maintaining oncogene expression in glioblastoma stem cells." (PMID 38474421, 2024). "Additionally, YTHDF2 promotes glioblastoma cell proliferation and tumorigenesis, largely through the downregulation of LXRα and HIVEP2." (PMID 38474421, 2024). "It has been shown that YTHDF2 regulates invasiveness of GSCs and glioblastoma cells." (PMID 38398118, 2024). "We hypothesized that YTHDF2 in glioblastoma could bind to m6A sites on APC and GSK-3β mRNAs, promoting their degradation and activating the Wnt-β-catenin pathway." (PMID 38637831, 2024). "YTHDF2 may have a role in glioblastoma adaptation to the tumour microenvironment, facilitating the maintenance of GSCs in the hypoxic niche and contributing to temozolomide resistance." (PMID 37444417, 2023). "In glioblastoma, YTHDF2 tended to be a therapeutic target; it could stabilize the transcripts of MYC and therefore regulate glucose metabolism in glioblastoma stem cells (GSCs)." (PMID 36686788, 2022). "Overexpression of YTHDF2 to regulate glucose metabolism in glioblastoma stem cells." (PMID 34093133, 2021). "For example, FTO promoted breast cancer progression by increasing the RNA degradation of the pro-apoptosis gene BNIP3 via m6A demethylation and a YTHDF2-independent mechanism and promoted glioblastoma tumorigenesis and cancer stem cell self-renewal as a component of the m6A regulatory machinery." (PMID 34218271, 2021). "Considering that PRMT6 promotes glioblastoma progression and Wnt-β-catenin pathway activation through YTHDF2, and that inhibiting its enzymatic activity reduces YTHDF2 expression, we explored whether this inhibition could suppress malignant phenotypes in glioblastoma." (PMID 38637831, 2024). "YTHDF1 and YTHDF2 were found to be highly overexpressed in glioblastoma (GBM) tissues compared to normal tissues." (PMID 36999016, 2023). "After 60 Gy radiation, YTHDF2 synthesis in GBM cells was significantly upregulated, suggesting that YTHDF2 plays an important role in TMZ resistance to recurrent glioblastoma." (PMID 36017491, 2022). "Furthermore, YTHDF2 inhibits LXRα-dependent cholesterol homeostasis in glioblastoma cells." (PMID 35625706, 2022). "Studies have shown that YTHDF2 mediates the downregulation of liver X receptor-alpha (LXRA) mRNA through m6A to influence glioblastoma (GBM) cholesterol homeostasis." (PMID 35004688, 2021). "In glioblastoma (GBM) stem cells, YTHDF2 was preferentially expressed, and it enhanced GBM growth via YTHDF2-MYC-IGFBP3 axis." (PMID 34804925, 2021). "In glioblastoma subtypes, MES subtype patients showed significantly higher YTHDF2 levels compared to PN subtype." (PMID 38637831, 2024). "Knockdown of YTHDF2 in GSC cells led to the suppression of in vitro cell invasiveness, whereas the overexpression of YTHDF2 in glioblastoma cells increased their invasion in vitro." (PMID 38398118, 2024). "YTHDF2 and PRADX decrease UBXN1 expression at the posttranscriptional level and thereby facilitate NF-κB signaling activity in glioblastoma and colon adenocarcinoma progression." (PMID 38773518, 2024). "YTHDF2 interacted with LXRA mRNA, resulting in the upregulated decay of LXRA mRNA and thereby promoting cell invasion of GSCs and glioblastoma cells." (PMID 38398118, 2024).
glioblastoma (continued). "These experimental results confirm that PRMT6 and YTHDF2 promote the EMT and invasive phenotype of glioblastoma in vivo, and PRMT6 promotes tumor malignancy in vivo by regulating the expression of YTHDF2." (PMID 38637831, 2024). "YTHDF2 is also involved in key signaling pathways, including the receptor tyrosine kinase MET pathway, which is essential for glioblastoma stem cell renewal and tumorigenicity." (PMID 38474421, 2024). "To understand how PRMT6 facilitates glioblastoma migration, invasion, and EMT through YTHDF2, we used TCGA and CGGA databases for GSEA pathway analysis." (PMID 38637831, 2024). "For example, in glioblastoma stem cells, m6A-modified MYC is recognized by YTHDF2, while in acute myeloid leukemia, it is recognized by IGF2BP2." (PMID 38879589, 2024). "The drug linsitinib is an IGF1/IGF1R inhibitor which was demonstrated to preferentially target YTHDF2-expressing cells, inhibiting GSC viability and impairing glioblastoma growth in vivo." (PMID 37444417, 2023). "YTHDF2 was also found to be upregulated in head and neck squamous cell carcinoma (HNSCC), ocular melanoma, and glioblastoma (GBM)." (PMID 35382893, 2022). "The YTHDF2 protein levels in glioblastoma cell lines (LN229 and U87 cells) and glioblastoma patient-derived N33 cells were also higher than those in anaplasia astrocytoma H4 cells and human astrocytes (HA)." (PMID 34246306, 2021). "We used the TCGA microarray database and compared the mRNA expression levels of five YTH domain family proteins, YTHDF1, YTHDF2, YTHDF3, YTHDC1, and YTHDC2, between 720 normal brain tissue microarray datasets and 582 glioblastoma datasets." (PMID 33317545, 2020). "In addition, YTHDF2 can maintain oncogene MYC and VEGFA transcripts in glioblastoma stem cells, thereby offering a therapeutic opportunity in glioblastoma." (PMID 40986143, 2025). "In addition, elevated levels were observed for RBM15B, WTAP, FTO, YTHDF2, YTHDF3, IGF2BP2, and IGF2BP3 in glioblastoma samples compared with normal brain controls." (PMID 38398118, 2024). "Finally, we investigated if the modulation of malignant biological behavior in glioblastoma by PRMT6 and YTHDF2 depends on the activation of the Wnt-β-catenin pathway." (PMID 38637831, 2024). "RIP-qPCR experiments demonstrated that YTHDF2 binds to APC and GSK-3β mRNAs in glioblastoma cells." (PMID 38637831, 2024). "Interestingly, data from GSE142825 showed that, in glioblastoma cells, KCTD15 mRNA expression was upregulated after YTHDF2 silencing, suggesting a negative regulatory role of YTHDF2 in KCTD15 mRNA stabilization." (PMID 38438714, 2024). "GSEA pathway analysis using TCGA and CGGA databases suggested that genes highly expressed in the YTHDF2 high-expression group are enriched in the EMT process, indicating that YTHDF2 might also promote EMT in glioblastoma." (PMID 38637831, 2024). "Also, YTHDF2 was found to stabilize MYC and VEGFA transcripts in glioblastoma stem cells in an m6A-dependent manner." (PMID 35526051, 2022). "Specifically, they found that an IGF1/IGF1R inhibitor targeting YTHDF2-expressing cells could suppress GSC viability and the growth of glioblastoma in vivo in an m6A-dependent manner." (PMID 34381710, 2021). "The phosphorylation of YTHDF2 stabilized the YTHDF2 protein and promoted the decay of LXRA and HIVEP2 mRNA, which is required for cholesterol dysregulation, cell proliferation, invasion, and tumorigenesis in glioblastoma." (PMID 33795663, 2021). "Thus, YTHDF2 links RNA epitranscriptomic modifications and GSCs growth, laying the foundation for the YTHDF2–MYC–IGFBP3 axis as a specific and novel therapeutic target in glioblastoma." (PMID 35625706, 2022). "In addition, YTHDF2 links RNA epitopic transcription modification to GSC growth, laying the foundation for the specificity of YTHDF2-Myc-IGFBP3 axis as a new therapeutic target for glioblastoma." (PMID 33673851, 2021).
glioblastoma (continued). "The IGF1/IGF1R inhibitor linsitinib preferentially targets YTHDF2-expressing cells, inhibiting GSC viability without affecting normal neural stem cells (NSCs) or impairing glioblastoma growth in vivo." (PMID 40469294, 2025). "Inhibition of IGFBP3, another FAM20C substrate and a downstream effector of the YTHDF2-MYC axis in glioblastoma stem cells (GSCs), decreases GSC viability without affecting NSCs and impairs glioblastoma growth in vivo." (PMID 36825005, 2023). "RIP-qPCR with antibodies against YTHDF1 and YTHDF2 showed that both YTHDFs strongly bound to ADAR1p110, ADAR1p150, and ADAR2 mRNAs in A172 glioblastoma cells, whereas ADAR3 was not expressed in A172 cells." (PMID 34324489, 2021).